IL4 (interleukin 4)
Diseases named in the same sentence as IL4 in open-access papers (continued):
Sharing a sentence is not in itself a finding about the gene and the disease.
atopic dermatitis (continued). "Dupilumab is a human monoclonal antibody targeting the interleukin-4 receptor (IL-4R) alpha subunit to block interleukin-4 (IL-4)/IL-13 signaling and to inhibit the inflammatory response that plays a role in the development of atopic dermatitis." (PMID 30026908, 2018). "These immunizations induced Th2 cell differentiation, which was promoted by IL-4 stimulation, and led to atopic dermatitis in lesional skin." (PMID 29662233, 2018). "Atopic dermatitis increased the expression levels of IL-4, IL-13, IL-6, IL-17, IFNγ, and TNFα but decreased the expression of IL-10 in BALB/c mouse, in an SOCS1-dependent manner." (PMID 30459600, 2018). "It has been shown that resveratrol provides protection against ADR via inhibition of the AKT/NF-κB signaling pathway as well as through suppression of high morbidity group box 1 (HMBG1), RAGE, TNF-α, and IL-4 in skin inflammation induced by atopic dermatitis." (PMID 29937497, 2018). "IL-4 derived from basophils was also shown to regulate the proliferation of skin ILC2s, which express the IL-4 receptor IL-4Rα, and induce atopic dermatitis-like disease." (PMID 28271445, 2017). "Serum levels of IgE and IL-4, which are increased in most patients with atopic dermatitis, were determined in the TMA-induced mouse model as a parameter for humoral (Th2) responses." (PMID 26825274, 2016). "Wound healing in a pre-existing Th2-dominated skin milieu was assessed by using an epidermal specific interleukin-4 (IL-4) transgenic (Tg) mouse model, which develops a pruritic inflammatory skin condition resembling human atopic dermatitis." (PMID 26752054, 2016). "While much has been published on the effects of excessive expression of IL-4/IL-13 on the skin barrier in inflammatory skin diseases such as atopic dermatitis (AD), the potential role of constitutive expression of IL-13 has hitherto been less well understood." (PMID 27357235, 2016). "Previous studies have demonstrated that elevated levels of IL-4 can lead to IgE synthesis in atopic dermatitis patients." (PMID 26404252, 2015). "Increased IL-4 is also reported to suppress IL-10, exacerbating syptoms of Th2 mediated atopic dermatitis." (PMID 25730203, 2015). "Experimental data suggest that melatonin inhibits development of atopic eczema and reduces serum total IgE and IL-4." (PMID 25093714, 2014). "Atopic dermatitis has been thought as a typical Th2 type immune disorder that expresses high levels of Th2 type cytokines such as IL-4, IL-5, and IL-13." (PMID 24499290, 2013). "Atopic dermatitis is thought to be a typical Th2 type immune disorder which shows elevated serum IgE level and increment of Th2 type cytokines such as IL-4, IL-5 and IL-13." (PMID 22988890, 2012). "The etiology and pathogenesis of atopic eczema is complex involving mainly T helper cells producing typical Th2 cytokines, such as IL-4 in early lesions, but dominated by the Th1 cytokine IFN-γ in the chronic phase." (PMID 21338426, 2011). "Th2 cells release cytokines, such as IL-4, IL-5, and IL-13, in allergic inflammation and atopic dermatitis." (PMID 21303540, 2011). "Our data, therefore, strongly supports the previously observed positive role of IL-4 in the transcription of FcεRIα-chain in human mast cells, eosinophils from atopic dermatitis patients, human dendritic cells, and human neutrophils." (PMID 19582151, 2009). "A combination of IL-4 and IL-13 was used as a Th2 cytokine mix, to resemble the atopic dermatitis cytokine microenvironment of active lesions." (PMID 18523683, 2008). "IL-4 has been reported to stimulate expression of JunB in peripheral blood monocytes from patients with atopic dermatitis." (PMID 17319946, 2007). "Moreover, studies have suggested that CXCL6 can be regulated by specific cell signaling pathways, such as the HIF-1α pathway in hepatocellular carcinoma and the IL4 pathway through the JAK-STAT mechanism in atopic dermatitis." (PMID 40070583, 2025).
atopic dermatitis (continued). "Studies have reported elevated levels of inflammatory cytokines, such as IL-4 and IL-13 and periostin, in the tear fluid of atopic dermatitis patients, which may exacerbate allergic responses on the ocular surface." (PMID 40718327, 2025). "Dupilumab, a fully human monoclonal antibody targeting the interleukin-4 receptor alpha (IL-4Rα), blocks both IL-4 and IL-13 signaling and is approved for several type 2 inflammatory conditions, including atopic dermatitis, asthma, and chronic rhinosinusitis with nasal polyposis." (PMID 40981278, 2025). "The role of interleukins IL-4, IL-5, IL-10, IL-13 and IL-33 in atopic dermatitis." (PMID 40771803, 2025). "GSVA revealed MC IL‐4 + IL‐13 signatures enriched in atopic dermatitis and psoriasis, IFNγ in COVID‐19 infection and cystic fibrosis, IL‐33 in COVID‐19 and chronic obstructive pulmonary disease (COPD) and TGFβ in pulmonary fibrosis (PF) and chronic rhinosinusitis." (PMID 40926620, 2025). "In atopic dermatitis, IL-13 and IL-4 produced by Th2 cells are known to promote the pathology, and monoclonal antibody preparations targeting IL-13/IL-4 receptors have become common treatments for atopic dermatitis." (PMID 39562488, 2025). "However, it is surprising that IL-4 and IL-13, while being key drivers of atopic dermatitis pathology, suppress 5-LO/ALOX5 expression." (PMID 41296013, 2025). "The role of IL-4 in the pathogenesis of warts is further supported by a case report in which a patient with atopic dermatitis and warts treated with dupilumab, an IL-4 inhibitor, experienced the resolution of both atopic dermatitis lesions and warts shortly after treatment." (PMID 40142865, 2025). "Likewise, while monoclonal antibodies against IL4 are already in clinical trials for atopic dermatitis, concerns remain regarding its side effects on immune susceptibility following continued use." (PMID 40055831, 2025). "One possibility is that IL-31 blockade induces compensatory upregulation of Th2 cytokines such as IL-4 and IL-13, which could partly explain the development or exacerbation of eczematous lesions, including atopic dermatitis." (PMID 41464561, 2025). "Similarly, we found elevated IL-4 levels in the plasma of three patients, reminiscent with findings in patients with atopic dermatitis." (PMID 41136770, 2025). "Thus, for patients who develop irBP as a side effect of cancer immunotherapy, IL-4 and IL-13 inhibitors such as dupilumab, so far approved to treat atopic dermatitis and prurigo nodularis, appear to be a promising new treatment option." (PMID 40507326, 2025). "Thus, JAK inhibition likely prevents the activity of IL-4/IL-13 involved in the inflammation of atopic dermatitis as well as treats the inflammatory arthritis due to its effect on curbing the IL-23/17 pathway." (PMID 39360077, 2024). "While CSU and atopic dermatitis (AD) can be clinically distinguished by specialist clinicians, they share significant similarities in their inflammatory mechanisms, particularly in the role of pro-inflammatory cytokines like IL-4, IL-5, IL-13, and IL-31." (PMID 38396704, 2024). "Atopic and allergic conditions, including atopic dermatitis, food allergies, atopic asthma, and allergic rhinitis, are all mediated by a Th2-type immune reaction, which involves the IgE antibody response, IL-4 and IL-5 cytokines, and tissue infiltration with eosinophils and mast cells." (PMID 38540315, 2024). "A potential link between IL-10 and eosinophilia may be supported by data from IL-10−/− mice showing diminished skin infiltration of eosinophils and IL-4 and IL-5 mRNA expression in a mouse model of allergic dermatitis." (PMID 39076967, 2024). "It was reported that Ech suppressed IL-4 and IL-13 in the atopic dermatitis model." (PMID 37750936, 2024).
atopic dermatitis (continued). "To get insight into the mechanism of the decline in OBP2A expression in atopic dermatitis lesional skin, we measured changes in OBP2A expression in human keratinocytes treated with type 2 cytokine IL-4 or IL-13, known to be involved in the pathogenesis of atopic dermatitis." (PMID 39502293, 2024). "Therefore, dupilumab is expected to suppress allergen sensitization by suppressing IL-4 signaling, thus suppressing IgE production, and to suppress allergen transcutaneous sensitization by controlling atopic dermatitis." (PMID 38785953, 2024). "Dupilumab is a monoclonal antibody that inhibits interleukin-4 (IL-4) and interleukin-13 (IL-13) signaling and is used in the treatment of moderate-to-severe atopic dermatitis (AD) in those six months or older who are uncontrolled on or cannot tolerate topical treatments." (PMID 39834978, 2024). "In addition, dupilumab is effective for chronic rhinosinusitis with nasal polyps and for atopic dermatitis, and IL-4/IL-13 blocking is expected to suppress allergen sensitization, including transcutaneous sensitization and atopic march." (PMID 38785953, 2024). "Additionally, DNCB-induced atopic dermatitis mice exhibited significantly increased Th2 (IL-4 and IL-13), Th1 (IFN-γ), and Th17 (IL-17A) cytokine mRNA levels in the cervical lymph nodes." (PMID 38672764, 2024). "In dogs with atopic dermatitis, serum IL‐13 increased more than IL‐4, suggesting that IL‐13 may play an important role in the development of the atopic response, compared to IL‐4." (PMID 38648253, 2024). "Moreover, T2-high cytokines, IL-4 and IL-13, play a key role in the pathophysiology of skin inflammation, such as atopic dermatitis." (PMID 39188724, 2024). "Similarly, the JAK-STAT signaling pathway is utilized by IL-4, IL-5, and IL-13 to induce Th2 immunity in Atopic Dermatitis." (PMID 39119011, 2024). "In addition, in chronic atopic dermatitis, excessive IL-4 production by Th2 cells stimulates B cells, leading to increased plasma IgE levels." (PMID 39519379, 2024). "Further, CM also suppressed the levels of IL-4 and IL-13 in Th2 cells, suggesting that CM may have therapeutic potential as a drug for atopic dermatitis." (PMID 38791236, 2024). "In addition, in the case of atopic dermatitis, the number of patients decreased further after 2017, the year in which new effective therapeutic options such as anti-IL4 and IL13 biologics and JAK inhibitors for atopic became available." (PMID 38076241, 2023). "However, antimicrobial peptides have been reported to induce the IL-4, IL-13, and IL-31 inflammatory pathways, which are hallmark features of atopic dermatitis, indicating that these peptides might function as a double-edged sword in the pathogenesis of atopic dermatitis." (PMID 37298299, 2023). "Nectin-1 distribution in atopic dermatitis skin and in IL-4/IL-13-treated human skin." (PMID 37289055, 2023). "On the other hand, excessive intake of linoleic acid may aggravate type 2 immune response as seen in atopic dermatitis with IL-4 and IL-13 overproduction." (PMID 37492568, 2023). "The FLG expression is downregulated in response to Th2-associated (IL-4, IL-13) and Th22-associated (IL-22) cytokines dysregulated in lesional and non-lesional skin of atopic dermatitis patients." (PMID 36904070, 2023). "For instance, high amounts of thymic stromal lymphopoietin (TSLP) in patients with atopic dermatitis activate T helper (Th) cells to produce Th2 cytokines (e.g., Interleukine (IL)-4, IL-5), which in turn can directly lead keratinocytes to further produce more TSLP." (PMID 37511139, 2023). "In primary keratinocytes, atopic dermatitis cytokines (IL-4, IL-13 and IL-31) significantly decreased mRNA expression of the barrier structure protein filaggrin (FLG) without histamine (0.3 ± 0.06-fold, p < 0.001) and in combination with histamine (0.24 ± 0.04-fold; p < 0.001)." (PMID 36615633, 2023). "IL-4 and TNF-α are risk factors for developing atopic dermatitis." (PMID 35646146, 2022).
atopic dermatitis (continued). "Although IL4-producing immune cells (e.g., basophils, mast cells, and Th2 cells) play a crucial role in Th2-mediated immune diseases such as atopic dermatitis (AD), DCs are also essential because they can initiate immune responses and modulate CD4+ T cell polarization." (PMID 36557876, 2022). "IL-17A can induce Th2 responses in murine models of atopic dermatitis and Th2 cells making both IL-4 and IL-17 have been seen in human allergic asthma and AD and may correlate with disease activity." (PMID 35265075, 2022). "Dupilumab inhibits the IL-4/IL-13 signaling pathway to reduce itching and itching in atopic dermatitis, which may reduce the release of CCL20 from keratinocytes and also reduce Th17 cell infiltration." (PMID 35069008, 2022). "For instance, dupilumab, a monoclonal antibody against IL-4, has been safely used in patients with atopic dermatitis and COVID-19, without increased risk of severe complications of the infection." (PMID 33995342, 2021). "Among them, dupilumab, a fully humanized IgG4 monoclonal antibody, targets IL-4/IL-13 signaling and displays strong efficacy as add-on therapy in severe uncontrolled asthmatic patients as well as in the T2 diseases atopic dermatitis and chronic rhinosinusitis with nasal polyps." (PMID 34572281, 2021). "While having effects on many different cell types, the main functions of the IL-4 and IL-13 pathways are the production of human immunoglobulin E and T-helper cell differentiation, which then brings on the clinical symptoms of atopic dermatitis, allergic rhinitis, and allergic asthma." (PMID 34948449, 2021). "We can hypothesize that, in atopic dermatitis, the axis IL-4-IL-13 is crucial in the pathogenesis of skin inflammation while IL-5/eosinophyl pathway is dispensable." (PMID 34680614, 2021). "Other cytokines, such as IL-4, IL-13, IL-31 and IL-33 play a key role in the pro-inflammatory and anti-inflammatory signaling pathways in patients suffering from inflammatory skin diseases such as psoriasis or atopic dermatitis." (PMID 33467067, 2021). "In addition, TSLP plays a critical role in the production of IL-4 from Th2 cells in atopic dermatitis through crosstalk between epithelial cells and dermal dendritic cells." (PMID 34946332, 2021). "IL-4 is present in bronchial asthma and atopic dermatitis patients." (PMID 34064515, 2021). "Properly speaking, it was able to restrain phosphorylation of MAPK and NF-κB in skin tissue, decrease the levels of interleukin-4 and IgE in serum, and reduce the expression level of various inflammation-related cytokines, thereby ameliorating the skin condition of atopic dermatitis." (PMID 34603060, 2021). "Increased IL-4 signaling was closely related to the development of pruritus with atopic dermatitis." (PMID 35431769, 2021). "IL-4 and IL-13 are classical Th2 cytokines, with a documented role in atopic dermatitis and asthma." (PMID 33544244, 2021). "In vivo studies in rodents showed that topical, inhalant or intratracheal applied TiO2 NPs alone worsened atopic dermatitis, induced lung injury (Interleukin-4 (IL-4) independent) and T helper-dependent inflammatory responses through ROS production and apoptosis." (PMID 33494245, 2021). "The IL-4 and IL-13 cytokine pathways play integral roles in stimulating IgE inflammation, with the IL-4 cytokine being a major cytokine in the etiology of thunderstorm asthma, atopic dermatitis, and allergic rhinitis." (PMID 34948449, 2021). "We also examined whether tapinarof, a potent AHR activator that is utilized clinically in the treatment of psoriasis and atopic dermatitis, has the same effect as Glyteer on IL-4-induced upregulation of IL-33 expression." (PMID 32214018, 2020). "Since PARP1 facilitates the expression of IL4 upon T-responses in a model of atopic dermatitis, PARP inhibitors may indirectly interfere with IL4-induced M2 polarization." (PMID 32900001, 2020).
atopic dermatitis (continued). "In addition, L. plantarum-derived EVs reduce inflammatory responses in S. aureus-induced atopic dermatitis mice by suppressing IL-6 and IL-4." (PMID 33233771, 2020). "As Th2 cytokines including IL-4 and IL-13 are pathological markers of atopic dermatitis, we analyzed the levels of these cytokines to determine whether perphenazine attenuates cytokine expression." (PMID 32375285, 2020). "The antioxidant and anti-inflammatory effects of water extracts of maqui berry were tested in a mouse dermatitis model showing an increase of interferon-gamma (IFN-γ) levels and a decrease of interleukin-4 (IL-4), suggesting its potential use for atopic dermatitis treatment." (PMID 31357475, 2019). "Hence, these mRNA expressions in NHEK upon stimulation with IL-4, one of the typical inflammatory cytokines in atopic dermatitis, was investigated." (PMID 30608955, 2019). "Along with TSLP and IL4/IL-13, CXCL10 may cause some of the symptoms of atopic dermatitis, although the role of this cytokine in the disease remains to be fully characterized." (PMID 31782733, 2019). "Recently, IL-4 has been shown to mediate itch by acting on its receptor, IL-4Rα, on sensory neurons, and deleting neuronal IL-4Rα effectively attenuates itch in a mouse model of atopic dermatitis." (PMID 31184997, 2019). "In mice with chemically-induced atopic dermatitis, potato extract alleviated the exacerbation of skin lesions by suppressing total serum level of IgE and maintaining T helper 1 (Th1; interferon-γ, and IL-12) and Th2 cytokines (IL-4 and IL-13) balance." (PMID 29495317, 2018). "Although S. aureus colonization has been strongly associated with atopic dermatitis, which is driven by Th2 responses, most components of the Th2 response such as IL-4, IL-5, and IL-13 were not induced by early colonization of S. aureus." (PMID 30185226, 2018). "Since IL-4 plays an important role in the pathogenesis of atopic dermatitis (AD), we further tested whether expression of FoxQ1 is changed in blood monocytes from AD patients compared to healthy donors." (PMID 29203829, 2017). "In atopic dermatitis, IL-4 is the main involved interleukin and may phosphorylate different JAKs in several cell types." (PMID 27711196, 2016). "In this study, we investigated whether Douchi attenuates protein kinase C (PKC) and interleukin (IL)-4 response and cutaneous inflammation in Atopic dermatitis (AD)-like NC/Nga mice." (PMID 27776525, 2016). "Besides, it has been shown recently in an elegant study that replacement of IL-4 and IL-13 by IL-17 in a combination of several cytokines led to the switch from an atopic dermatitis-like to a psoriasis-like three dimensional in vitro model." (PMID 26656739, 2015). "IL-4 and IL-13 induce immunoglobulin E (IgE) production in vitro, and their mRNA levels are strongly up-regulated in biopsy specimens of allergic contact dermatitis as well as atopic dermatitis patients." (PMID 23531535, 2013). "Th2 cells produce IL-4, IL-5, and IL-13 and play major roles in acute atopic dermatitis." (PMID 24499290, 2013). "IL-22, TNFa, IL-4, and IL-13 combination is able to mimic an “atopic dermatitis like” state." (PMID 23193414, 2012). "An immunohistochemical examination of the skin lesions in NC/Nga atopic model mice revealed the typical features of affected skin observed in patients with atopic dermatitis, such as increased infiltration of T cells, mast cells, and substantial expression of IL-4 and IL-5." (PMID 21303540, 2011). "Furthermore, in a model of 2,4-dinitrochlorobenzene (DNCB)-induced atopic dermatitis in mice, topical application of verbascoside reduced scratching and skin lesion severity, lowered IgE and IL-4 and IL-13 levels, and decreased inflammatory cytokines (TNF-α, IL-6, IL-4) in affected skin." (PMID 40724000, 2025).